TLCD4 (TLC domain containing 4)
Synonyms: TMEM56; FLJ31842
Tractability: Antibody: UniProt predicts a signal peptide or a membrane-spanning region.
Gene: Protein-coding gene on chromosome 1 (95,117,292 to 95,197,607, forward strand). Ensembl gene ENSG00000152078.
Subcellular location: Membrane
Subcellular location (Human Protein Atlas): Nuclear speckles
Gene Ontology:
Molecular function: protein binding
Biological process: lipid homeostasis
Cellular component: endoplasmic reticulum; membrane
Genetic constraint (gnomAD): Loss-of-function variants: 7 observed, 24.93 expected, observed/expected ratio (o/e) 0.28, 90% interval 0.16 to 0.53. The upper end of that interval is the gene's LOEUF score, 0.53, which puts it in group 2 of 6, group 1 being the genes least tolerant of losing a copy. Missense variants: 259 observed, 308.31 expected, observed/expected ratio (o/e) 0.84, 90% interval 0.76 to 0.93. Synonymous variants: 103 observed, 106.06 expected, observed/expected ratio (o/e) 0.97, 90% interval 0.83 to 1.14.
Homologues: Orthologues: chimpanzee TLCD4 (99% identical), rabbit TLCD4 (83% identical), dog TLCD4 (81% identical), guinea pig TLCD4 (77% identical), mouse Tlcd4 (77% identical), rat Tlcd4 (76% identical), pig TLCD4 (65% identical), zebrafish tlcd4a (55% identical), tropical clawed frog tlcd4 (54% identical), zebrafish si:dkey-10f21.4 (49% identical). Paralogues in human: TLCD3A (19% identical), TLCD3B (17% identical), TLCD2 (16% identical), CLN8 (14% identical), TLCD1 (13% identical).
Diseases named in the same sentence as TLCD4 in open-access papers:
TLCD4 is named in the same sentence as 13 diseases in open-access papers, as found by Europe PMC text mining. Sharing a sentence is not in itself a finding about the gene and the disease. The quoted sentences say what the papers report.
Sepsis (3 papers, 2021 to 2024). Sepsis is defined as life-threatening organ dysfunction caused by a dysregulated host response to infection. "Studies uncovered that the ribosome-related genes TLCD4, PRSS30P, and ZNF493 had a moderate performance to identify sepsis-induced acute respiratory distress syndrome (ARDS) in sepsis patients." (PMID 36299685, 2022). "Three genes–TLCD4, PRSS30P, and ZNF493 indicated moderate performance in distinguishing sepsis-induced ARDS from sepsis." (PMID 33818300, 2021). "Feature selection analysis revealed that three genes, TLCD4, PRSS30P, and ZNF493, showed moderate performance in identifying sepsis-induced ARDS from sepsis." (PMID 33818300, 2021). "We performed feature selection analysis and found that combination of three genes (TLCD4, PRSS30P, and ZNF493) and seven genes (TLCD4, PRSS30P, ZNF493, AGO2, SLC37A3, SLC2A1, and RPL11) showed moderate performance in identifying patients with sepsis and ARDS within 1 day after admission." (PMID 33818300, 2021).
Obesity (1 paper, 2024). Accumulation of substantial excess body fat. "On the other hand, TLCD4 expression was not affected either by cold exposure or post-absorptive fasting in women with overweight/obesity." (PMID 39199323, 2024).
TLCD4 also shares sentences with these, for which no sentence is quoted: hypertrophic cardiomyopathy (4 papers); acute respiratory distress syndrome (2); glioma (2); Hypertension (2); acute myeloid leukemia (1); bipolar disorder (1); cardiomyopathies (1); coronary heart disease (1); depression (1); neurological disorders (1); viral hepatitis C (1).